CD86 (CD86 molecule)
Diseases named in the same sentence as CD86 in open-access papers (continued):
Sharing a sentence is not in itself a finding about the gene and the disease.
colitis (continued). "Taken together, our results may highlight a novel aspect of IECs as a IL-17A-inducer in murine colitis, and that costimulatory molecules in IECs such as CD80/CD86 and CD40 may be a therapeutic target for colitis." (PMID 24255712, 2013). "In addition, a direct pathological role for CD80 and CD86 in UC has been postulated, and blockade of CD80 suppresses colonic inflammation in a murine colitis model." (PMID 20360984, 2010). "Similarly, CD86+ and CD11c+ cells were decreased in probiotic-mixture-treated colitis mice in PPs compared to the non-treated colitis mouse group." (PMID 39201260, 2024). "We here carried out immunofluorescence staining with F4/80 as the marker of macrophages, CD86 as the marker of M1 phenotype, and CD206 as the marker of M2 phenotype to evaluate the effect of integrin β6 deletion on macrophage infiltration and polarization in colitis tissues." (PMID 37223685, 2023). "Notably, experimental colitis did not increase IL-1ß expression in the mPFC, despite increasing TNF-α and CD86 expression." (PMID 31882991, 2019).
lupus (34 papers, 2006 to 2025). "In this study, the elevated expression of CD86 and iNOS in lupus mice could be strongly associated with kidney inflammation and tissue injury." (PMID 41161814, 2025). "CD11b B1 cell frequency was significantly elevated in lupus patients, and they expressed a higher level of CD86, thus facilitating the stimulation of CD4 T cells." (PMID 39960645, 2025). "however, in contrast to autoimmune hepatitis, CD11b+ B cells in lupus patients express more CD86 and have increased T cell–stimulating activity." (PMID 38313293, 2024). "As expected, compared with IMQ-treated mice that received control MDSCs, IMQ-treated mice that received lupus MDSCs showed significantly higher levels of CD86 on splenic macrophages and DCs." (PMID 38429401, 2024). "The current study demonstrated the specific stimulatory effects of hCG on the expression of CD40 and CD86 on B cells derived from lupus-prone mice, in conjunction with two TLR ligands, both of which have been implicated in lupus." (PMID 30574119, 2018). "KEGG analysis revealed the systemic lupus erythematosus pathway involving CD86, TNF, C4, FCGR2B, CD80, C3, CD40, and C1S." (PMID 28976997, 2017). "In BXD2 lupus-prone mice, it was demonstrated that the accumulation of activated pDC in the MZ of spleen resulted in the upregulation of CD86 on MZ B cells, which was important for germinal center (GC) formation and autoantibody production." (PMID 27034965, 2016). "Consistent trends toward decreased proportions of mature naïve and CD86+ naïve B cells were seen when the first-degree relatives of lupus patients were segregated into parents and siblings, but these were less pronounced in the siblings." (PMID 18783591, 2008). "Besides, CD11b B1 cell frequency was markedly elevated in lupus patients, and these cells secreted modest levels of antibodies and enhanced T-cell stimulatory activity through CD86." (PMID 39960645, 2025). "A mAb against human CD86(1D1) has been developed which could prevent the development of chronic graft-versus-host disease (cGVHD)-induced lupus." (PMID 40211396, 2025). "Moreover, we also noted that the activation markers (MHC II, CD80, and CD86) on dendritic cells were significantly elevated in spontaneous lupus NZM2328 mice that were fed the HSD diet compared with those that were fed the NSD diet." (PMID 32296043, 2020). "cDC in the blood of SLE patients or secondary immune tissues of lupus-prone mice have been shown to exhibit elevated expression of CD40, CD80, CD86, PD-L1, and PD-L2, suggesting that cDC in lupus may be activated and immunogenic." (PMID 27034965, 2016). "Interestingly, DCs from lupus patients show higher expression of co-stimulatory molecules, such as CD86 and CD40, than DCs from healthy controls suggesting an immunogenic prone state for these cells." (PMID 25229821, 2014). "Indeed, there was a highly significant reduction in the proportion of CD86+ naïve B cells in the family members of lupus patients as compared with control individuals." (PMID 18783591, 2008). "Because these data were collected from a large number of mice, especially in the adult populations, and in separate experiments over a period of months, such consistency strengthens the significance of the altered expression ratio of CD80 to CD86 observed in adult mice with lupus." (PMID 16507174, 2006). "In our studies, we found that elevation of the expression level of miR-1246 in lupus B cells could decrease the expression of EBF1 causing the downregulation of CD40, CD80, and CD86 which are co-stimulatory molecules required for full B cell activation and IgG secretion." (PMID 25789080, 2015). "In agreement with previous studies, the expression of CD80, CD86, and CD40 after culture with LPS was diminished in moDC from lupus patients compared with healthy controls." (PMID 27057555, 2016).
lupus (continued). "Our group has shown lupus patients have an increased expression of co-stimulatory molecules such as CD40 and CD86, suggesting that DCs immunogenicity is augmented." (PMID 25229821, 2014). "In the 3 lupus patients studied, MDDCs responded to LPS stimulation with increased expression of HLA-DRII, CD40, and CD86." (PMID 20169063, 2010). "In diabetic mice and in lupus-prone MRL/lpr mice, the blockade of CD80 worsens the severity of both diseases, whereas blockade of CD86 prevents diabetes and has mild effects on lupus." (PMID 16507174, 2006). "We found that DCs from lupus-prone mice expressed levels of CD80 and CD86 comparable to those ofBALB/c and B6 DCs, in terms of both percentage of positive cells and MFI (not shown)." (PMID 16507174, 2006). "Whereas the alteration in CD80/CD86 ratio is evident only after the onset of the disease, the overexpression of CD40 precedes the onset of lupus and is sustained even during the course of the disease." (PMID 16507174, 2006). "We found that in lupus-prone mice, after the onset of the disease, DCs expressed an abnormal state of activation with decreased levels of CD80 and CD54, normal levels of CD86, and a specific increase in cells expressing CD40." (PMID 16507174, 2006). "We show here that DCs from diseased NZM2410 lupus-prone mice have an altered costimulation pattern, with an abnormal ratio of CD80 to CD86 due to decreased levels of CD80 and normal levels of CD86." (PMID 16507174, 2006). "DCs from young lupus-prone NZM2410 mice, before the development of the disease, expressed normal levels of CD80 and CD86 but already overexpressed CD40." (PMID 16507174, 2006). "Several other studies did not observe an increase in CD86 levels on monocytes, including monocytes from patients with systemic lupus erythematosus." (PMID 40936922, 2025). "Among the surface molecules, the expression of CD55, CD86, CD93, and CCR6 were decreased in G-MDSCs from pristane-induce lupus mice, and INK128 could increase the expression of these genes." (PMID 34282122, 2021). "Our previous study showed that CD14+CD16+ monocytes in patients with systemic lupus erythematosus showed inflammatory phenotype, with increased CD80, CD86, HLA-DR, and CX3CR1, which could promote Th17 response." (PMID 32958023, 2020). "In addition, we found the UC-MSCs induced CD1c+DCs in the lupus patients exerted tolerogenic properties by decreasing expression of CD80, CD83, CD86 and HLA-DR, decreasing production of TNFα and keeping production of IL-10." (PMID 31175312, 2019). "The upregulation of CD86 but not CD80 on APCs is observed in other diseases as well such as systemic lupus erythematosus." (PMID 27348308, 2016). "Lupus patients had significantly increased proportions of activated B cells, as demonstrated by the increased percentage of CD20+ cells with elevated levels of CD69 and increased proportion of CD86+ cells in the CD27+ B-cell compartment." (PMID 18783591, 2008). "Moreover, the comparable levels of CD80 and CD86 in BALB/c and B6 DCs confirmed the feasibility of using these two strains of mice for comparison with the lupus-prone strain." (PMID 16507174, 2006). "Lupus DCs showed an altered ex vivo costimulatory profile, with a significant increase in the expression of CD40, decreased expression of CD80 and CD54, and normal expression of CD86." (PMID 16507174, 2006). "However, the maturation and activation markers on dendritic cells, including MHC II, CD80, and CD86, were significantly increased in cells that were isolated from sodium chloride-pretreated BMDC-ALD-DNA-induced lupus mice compared to those of control lupus mice." (PMID 32296043, 2020). "Despite previous reports in the literature indicating increased autoantibody production in the relatives of lupus patients, the proportions of activated B cells, as determined by expression levels of CD69, CD80, and CD86, were not increased in the family members of our lupus patients." (PMID 18783591, 2008).
lupus (continued). "An increase in the maturation phenotype of DCs, such as upregulated expression of co-stimulatory molecules, such as CD86, and increased secretion of pro-inflammatory cytokines, such as IL-12 and IFN-I, have been documented in systemic lupus erythematosus (SLE) patients." (PMID 37183207, 2023). "In this study, we evaluated the gene polymorphisms of the ligand genes corresponding co-stimulatory system that were expressed on antigen-presenting cells (CD80, CD86, ICOSLG, and PDL1) from 60 systemic lupus erythematosus (SLE) patients and 60 healthy controls." (PMID 38361527, 2023). "As expected, injection of anti-CD180 Ab could significantly reduce the levels of CD86 on peritoneal macrophages, splenic macrophages and DCs from MRL/lpr mice, indicating that ligation of CD180 can inhibit the activation of macrophages and DCs in vivo and ameliorates lupus-symptoms in MRL/lpr mice." (PMID 30498494, 2018). "However, the geometric mean expression of CD86 in non-classic monocyte subsets was still higher in lupus patients than controls (P = 0.005, data not shown) after removing two outliers of patients, indicating that monocytes are activated in vivo in patients compared to controls." (PMID 25485543, 2014).
asthma (32 papers, 2008 to 2025). "Several studies showed that CD86 level is upregulated in patients with asthma and allergic diseases and is closely associated with Th2 reactions and airway inflammation." (PMID 33746954, 2021). "SNPs located in five genes, including IL10, CYP24A1, IL1RL1, CYP2R1 and CD86, showed modest association with asthma or atopy in an asthma family study derived from the Saguenay_Lac-Saint-Jean population." (PMID 19852851, 2009). "A number of SNPs in the IL10, CYP24A1, CYP2R1, IL1RL1 and CD86 genes were modestly associated with asthma and atopy (p < 0.05)." (PMID 19852851, 2009). "Different SNPs in the CD86 gene were also associated with asthma in the CAPPS and BHS studies." (PMID 19852851, 2009). "Accordingly, different CD86 polymorphims were associated with asthma in three populations." (PMID 19852851, 2009). "Thus, evidence is building to implicate CD86 as a susceptibility gene for asthma, but independent replications in larger population samples are required." (PMID 19852851, 2009). "Again modest associations were observed for the IL10, CYP24A1 and CD86 genes for asthma or atopy." (PMID 19852851, 2009). "The AS group exhibited a significant increase in CD86 expression in both total DCs and specifically within the CD11b+ DC subset, indicating enhanced activation of CD11b+ DCs in asthma." (PMID 40405264, 2025). "HDM allergens also engage TLR2 in dendritic cells to upregulate c-kit and costimulatory molecules (CD80/CD86), thereby polarizing Th2 responses and exacerbating asthma." (PMID 40529570, 2025). "The level of CD86 is significantly increased in patients with an acute asthma exacerbation and correlated with the severity of asthma." (PMID 38082274, 2023). "Long-chain non-coding RNA n337374 relieves symptoms of respiratory syncytial virus-induced asthma by inhibiting dendritic cell maturation via the CD86 and the ERK pathway." (PMID 35241728, 2022). "In a previous study in adults we identified airway DC in induced sputum samples using flow cytometry and that DC from patients with asthma are more mature compared with healthy controls, as evidenced by a higher proportion expressing increased CD86." (PMID 32369498, 2020). "It is noteworthy that exposure with crude O. felineus extract leads to the downregulation of costimulatory molecules CD83 and CD86 in LPS-induced DCs, generated from monocytes of asthma patients." (PMID 31750318, 2019). "Moreover, in another immune tolerance-related disease, like asthma, the authors made hypothesis that the CD86 gene, as a part of the vitamin D pathway, is associated with susceptibility to the disease; especially, the rs2715267 SNP was associated with the modest risk of atopy and asthma." (PMID 29577049, 2018). "The results showed that pulmonary DCs from OVA-sensitized and -challenged mice treated with MSCs showed reduced expression of CD40, CD80 and CD86 compared with those in the PBS-treated asthma group." (PMID 25936350, 2015). "We investigated the effects of the downregulation of CD86 by short interfering RNAs (siRNAs) on Th2 cytokine production in the effector phase in vitro and on asthma phenotypes in ovalbumin (OVA)-sensitized and -challenged mice." (PMID 25344652, 2014). "Here, we examined the effects of the downregulation of CD86 by intratracheal administration of siRNA on Th2 cytokine production in the effector phase in vitro and on asthma phenotypes in vivo." (PMID 25344652, 2014). "We have shown that local administration of CD86 siRNA during the effector phase ameliorates lines of asthma phenotypes." (PMID 25344652, 2014). "A previous study have also reported elevated levels of CD80 and CD86 in patients with asthma." (PMID 40697948, 2025). "By using mass cytometry (CyTOF), we found that VISTA deficiency primarily increased lung macrophage infiltration in the OVA-induced asthma model, accompanied by an increased proportion of M1 macrophages (CD11b+F4/80+CD86+) and a decreased proportion of M2 macrophages (CD11b+F4/80+CD206+)." (PMID 38340268, 2024).
asthma (continued). "The expression of CD86 in B cells was significantly increased in asthma patients." (PMID 35052792, 2022). "CD86 was the only good biomarker for asthma-severity discrimination." (PMID 29977241, 2018). "CD86 is another target which was firstly tested using ASO knockdown in an asthma model." (PMID 28106744, 2017). "It has also been demonstrated that CD80 and CD86 are critical and potent stimulators of Th2 differentiation in vitro and that these molecules are essential for the generation of Th2 cells during the sensitization phase in a murine model of asthma." (PMID 25973430, 2015). "The relevance of CD86-targeted approach in various asthma phenotypes awaits further investigations." (PMID 25344652, 2014). "CD86+ B cells are the subpopulation of B cells that secrete IgE, which correlates with the increased serum IgE seen in the patients with Alternaria-sensitive moderate-severe asthma." (PMID 20298583, 2010). "In this model, the risk of asthma is similar for carriers of two common CD86 alleles irrespective of the IL10 genotypes, however, the risk increases additively with the number of rare alleles in the two genes." (PMID 19852851, 2009). "In the present study, however, treatment with CD86 siRNA abolished the OVA-challenge-induced elevation of IL-13 in BAL fluid, which makes it difficult to explain the differences in the effects of siRNA via variant sensitivities of IL-13-mediated asthma phenotypes to therapeutic interventions." (PMID 25344652, 2014). "A decrease in CD86 expression is thought to suppress DC maturation, prolonging allograft survival in heart-transplanted mice and relieving RSV-induced asthma." (PMID 39473751, 2024). "In asthma, dendritic cells present antigens to CD4 + T cells by expressing MHC class II molecules and rely on co-stimulatory molecules such as CD40, CD80, CD86 to induce T cell activation." (PMID 38664707, 2024). "Previously reported overexpressed (IL-10, MSR1, PHLDA1, SERPINB2, and CD86) and underexpressed genes (CHI3L1, CPA3, IL-8, and PI3) in severe asthma were analyzed by RT-qPCR in peripheral blood mononuclear cells (PBMCs)." (PMID 37445432, 2023). "In the second place, studies have pointed out that asthma and RA may have overlapping genetic predispositions, and certain genetic variants in immune-related genes are associated with increased susceptibility to asthma and RA, such as HLA-DRB1, CD40L, and CD86." (PMID 36869337, 2023). "Eosinophils have been found to accumulate and become activated in airways of asthma patients or murine models during virus-induced exacerbations, manifested by increased expression of CD80, CD86, and MHC II." (PMID 35185908, 2022). "In particular, seven gene targets (HMGCR, ADORA1, IL6R, CD86, BCR, PIK3CD, and NOS1) are prioritized for asthma drug repurposing." (PMID 35052792, 2022). "A marked downregulation in the expression levels of CD80, CD86 and MHC class II was observed in the lung DCs of the mice in the anti-NGF group when compared with the mice in the asthma and control IgG groups." (PMID 25289030, 2014). "The expression levels of CD80, CD86 and MHC class II on the lung DCs were found to be upregulated in the mice in the asthma and IgG control groups, as compared with the control group." (PMID 25289030, 2014). "To explore whether CXCL16 knockout alters the expression of costimulatory cell surface molecules in response to Aspergillus-induced asthma, we detected the expression of CD80 and CD86 of the DCs in lung tissue cells for flow cytometry." (PMID 40050290, 2025). "Additionally, our bioinformatic networking analysis also showed that CD86 and NOS1 are promising targets for asthma drug repurposing." (PMID 35052792, 2022). "Gene silencing of CD86 by siRNA also decreased airway eosinophilia, BAL fluids IL-5 and IL-13, and CCL17 production, serum OVA-specific IgE levels, and AHR in an OVA-induced mouse asthma model." (PMID 28106744, 2017).
asthma (continued). "However, decreased expression levels of CD80, CD86 and MHC class II were observed in the lung DCs of the mice in the anti-NGF group, as compared with those in the asthma and control-IgG groups, despite increased serum levels of IFN-γ." (PMID 25289030, 2014). "Contrasting with the effects on lines of asthma phenotypes, CD86 siRNA treatment failed to ameliorate the goblet cell hyperplasia and MUC5AC gene expression, cardinal features of airway remodeling in asthma." (PMID 25344652, 2014). "Notably, neither CD86 nor OX40L expression was altered in the CD103+ DC subset, further reinforcing that acupuncture specifically targets the CD11b+ DC population and its immunostimulatory activity, thereby mitigating airway inflammation in asthma." (PMID 40405264, 2025).